FOXM1 (forkhead box M1)
Diseases named in the same sentence as FOXM1 in open-access papers (continued):
Sharing a sentence is not in itself a finding about the gene and the disease.
tumor (continued). "Furthermore, immunoblotting assay also showed that the protein levels of MELK, phospho-FOXM1 (T600), and its downstream targets (PLK1, Cyclin B1 and Aurora B) were much higher in tumor cell lysates derived from MELK-overexpressing mice than those from the control group." (PMID 32047721, 2020). "Therefore, we hypothesized that FOXM1 is a key target of RAME; this could result in its anti-tumor effects." (PMID 33053721, 2020). "Additionally, we found PTTG3P could be transcriptionally activated by FoxM1, thus forming a potent feedforward circuitry to enhance PTTG3P-induced pro-tumor effect." (PMID 33298873, 2020). "FSCN1 expression was found to be positively correlated with ACC tumour purity (r = 0.349, p = 2.33e− 03), and negatively correlated with the infiltration signature of CD8+ T cells (r = − 0.372, p = 1.19e – 03), while FOXM1 showed a weak correlation with B cell and dendritic cell signatures." (PMID 31783819, 2019). "FOXM1 has been demonstrated to crosstalk with the TGF-β and Wnt pathways and its expression is correlated with MMP-2, MMP-9, VEGF, and urokinase-type plasminogen activator (uPA), and hence, FOXM1 can modulate angiogenesis, migration, and proliferation of tumor cells." (PMID 31887997, 2019). "Using our previous microarray dataset, we determined that the expression of EZH2, RRM1 and FOXM1 was significantly increased in tumor compared with the non-tumor lung tissue and the expression of BTG2, NFIB and SELENBP1 was significantly decreased in the tumor compared to non-tumor." (PMID 30458017, 2018). "PDX mouse models from two TNBC patients were established: PDX1 was from a tumor with low FOXM1 protein expression and a small fraction of side population cells (0.2%), while PDX2 was from a tumor with relatively higher expression of FOXM1 and higher proportion of side population cells (5%)." (PMID 30572639, 2018). "Given that mitotic kinesins are frequently overexpressed in tumor cells and that certain kinesins have been identified as novel target genes of MuvB, B-MYB and FOXM1, we sought to determine the mitotic kinesins that are directly regulated by MuvB, B-MYB and FOXM1." (PMID 28061449, 2017). "Thus our results with the mammalian two-hybrid system indicate that SLPI protein physically interacted with Rb tumor suppressor but not FoxM1, and also confirmed the known interaction of Rb and FoxM1 proteins." (PMID 29312532, 2017). "We first merged target genes identified in each cell line into a core set of FOXM1 target genes and employed the BASE algorithm to calculate an individual Regulatory Activity Score (iRAS) for each tumor sample based on the expression of FOXM1 target genes in the tumor gene expression profile." (PMID 29100329, 2017). "These tumor tissues were classified into two groups (positive + or negative –), and the positive tissues were further graded into four levels according to the degrees of FOXM1 or ABCC5 expression (negative, +, ++, +++)." (PMID 28277541, 2017). "FOXM1 is up-regulated in all three major EOCs subtypes, and is a prognostic biomarker and a potential combinatorial therapeutic target in platinum resistant disease, irrespective of tumor histology." (PMID 28482906, 2017). "Furthermore, research in the mechanism found PVT1 could target genes such as LASP1, FOXM1, RSPO1, p15, p16, EZH2, TSHR, and NOP2 to promote tumor cell proliferation, migration and invasive capability in vitro." (PMID 29088881, 2017). "Immuno-histochemical (IHC) was used to detect the expression of FOXM1 in xenograft tumor." (PMID 27716361, 2016).
tumor (continued). "We also identified six UPRs unique to CPA-treated B16F10 tumors vs. GL261(B6) tumors that promote tumor cell survival or tissue repair and may contribute to B16F10 tumor unresponsiveness: activated UPRs KDM5B, RBL2 and SPARC; and inhibited UPRs FOXM1, CD24 and CSF2)." (PMID 27515027, 2016). "Conversely, when tumor size is larger, the five-year survival was significantly worse in those with positive FOXM1 expression than negative ones, indicating that FOXM1 expression significantly shortened the survival in patients with larger tumor size (P = 0.004)." (PMID 24004449, 2013). "Since TOPO-2α is a prominent target for anti-tumor therapy due to its critical role in tumor cell proliferation, we focused our next experiments to determine whether TOPO-2α gene is a direct transcriptional target of Foxm1." (PMID 19672312, 2009). "Based on these findings, we argue that the combination of FOXM1 inhibition and PARPi may prove an efficient therapeutic strategy for OC in the maintenance setting, due to its potential to synergistically interfere with OCSC-driven chemoresistance and tumor recurrence." (PMID 38806454, 2024). "In this study, FOXM1 may be phosphorylated by cytoplasmic ABL1 in response to stimuli and induces tumorigenesis, while FOXM1 phosphorylated in the nucleus contributed to cell proliferation, particularly in the cells with ABL1 overexpression and activation, especially in the tumor cells." (PMID 39060421, 2024). "We will also consider likely mediators of acquired resistance to such therapies, particularly Forkhead box protein M1 (FOXM1) and programmed death-ligand 1 (PD-L1), whose simultaneous inhibition may be needed to achieve sustained, and possibly curative, anti-tumor activity." (PMID 39347707, 2024). "Overall, these data demonstrated that the TME-induced FOXM1 upregulation is a vulnerability of OCSC, and can render them more responsive to PARPi, thus suggesting that a combinatorial treatment in the maintenance setting could successfully delay, or even prevent, tumor recurrence." (PMID 38806454, 2024). "Treatment with MEKi significantly blunted tumor growth of CDK4i/6i-resistant ALM cells, and the combination of CDK4i/6i + MEKi resulted in the greatest antitumor activity and decrease in cell cycle proteins (pRb, cyclin D, PLK1, FOXM1) relative to what could be achieved by the single-agents alone." (PMID 38066089, 2024). "Tumor type and RB1 context may affect exactly how FOXM1 expression influences CDK4/6 inhibitor efficacy, meriting further investigation, but there is growing evidence that FOXM1 plays a key role in determining tumor cell responsiveness and resistance to CDK4/6 targeting." (PMID 37686402, 2023). "The interaction network showed that FOXM1 was closely correlated with those proteins who are involved in the cell cycle, such as cyclin-dependent kinase 1 (CDK1), CDK2, Cyclin B1 (CCNB1), as well as CCNB2, indicating FOXM1 may act as an important regulator of the tumor cell cycle." (PMID 37159818, 2023). "First, we found the co-overexpression of FOXM1 and CENPF in HCC was associated with aggressive tumor behavior, including the presence of venous invasion, tumor microsatellite formation, and the absence of tumor encapsulation by clinicopathological correlation analysis." (PMID 35865168, 2022). "Thus, overexpression of CCAT2 might be responsible for the mitigation of the tumor suppression ability of miR-34a, which has been also shown to promote the activation of cellular senescence programs by downregulating the FOXM1 oncogene independent of CCAT2." (PMID 34830370, 2021). "Moreover, inhibition of FOXM1 or H3K79me2 could suppress tumor development in TBM, while the absence of CD8+ T cells in TBM abolished the effect." (PMID 30628173, 2019).
tumor (continued). "In this study, we found that FOXM1 signaling was significantly associated with PTC progression, regardless of tumor stage and histological subtypes, indicating that the expression of genes related to FOXM1 signaling in the primary tumor might confer the potential for PTC progression." (PMID 28187428, 2017). "However, the role that FOXM1 might play in engendering resistance to endocrine treatments in estrogen receptor-positive (ER+) patients when tumor FOXM1 is high has not been clearly defined yet." (PMID 25213081, 2014). "The FOXM1 SUCC has not been researched, while a previous study indicates that FOXM1 protein can be modified by other post-translational modifications, including phosphorylation, ubiquitination, Ace, and methylation, which may have activator or inhibitory effects on the tumor progression." (PMID 39020302, 2024). "Recently, we have identified a small molecule inhibitor of FOXM1 (Robert Costa Memorial Drug-1, RCM1) that has shown to be an effective anti-tumor agent and is also non-toxic in pre-clinical mouse models." (PMID 36816948, 2023). "Concurrent expression of IFITM1, FOXM1, and PLK1 showed a high correlation with tumor formation in primary and advanced LUAD but not in LUSQ." (PMID 37968723, 2023). "DKK1- or FOXM1-positive cells were only minimally detected in the non-tumor epithelium, whereas tumor lesions showed clear staining for DKK1 and FOXM1." (PMID 34117362, 2021). "In summary, the observed remarkable negative correlation between miR-320d and FoxM1 in human GCA specimens, GCA cell lines, and GCA tumor-bearing mice, are achieved." (PMID 32551039, 2020). "FOXM1 expression is enhanced by EWS/FLI1, though, unlike other tumor systems, it is not driven by expression of the EWS/FLI1 target GLI1." (PMID 23365673, 2013). "In only one of the tumor types (THCA), FOXM1 was not upregulated when compared to normal tissue." (PMID 39858603, 2025). "However, the upregulated methylation levels of FOXC2, FOXF1, FOXF2, FOXM1, and FOXN3 indicated that an epigenetic mechanism was not the main reason for the elevated FOX expression in tumor tissues." (PMID 36622275, 2023). "To validate FOXM1 and CENPF expression in our cohort of HCC patients, we examined the abundance of mRNA expression of FOXM1 and CENPF in 118 randomly selected pairs of HCC clinical samples (tumor, HCC, and corresponding non-tumorous liver tissues, NT) by real-time RT-PCR analysis." (PMID 35865168, 2022). "The correlation between the ratios of tumor lesions stained with DKK1 and FOXM1 was confirmed, namely an ESCC tumor lesion which highly expressed DKK1 was also positive for FOXM1, and a tumor lesion which did not express DKK1 was negative for FOXM1." (PMID 34117362, 2021). "The other cell cycle genes analyzed (PLK1, FOXM1, MKI67) were downregulated in romidepsin-treated spheres and PDX-Os but were not changed after romidepsin treatment of the cell line (FOXM1 was increased in the cells) nor tumor implants." (PMID 33035223, 2020). "The second mechanism discovered, although not directly determined by SLPI secretion from tumor cells, is clearly connected with intracellular SLPI production, which operates via FoxM1 intracellular regulation to alter the expression of other secretory proteins with pro-metastatic activity." (PMID 29312532, 2017). "In addition, Western blot analysis revealed that protein levels of FOXM1 and HSPA5 were upregulated in tumor samples relative to normal tissues." (PMID 27034162, 2016). "Thus, FOXM1 overexpression was not sufficient to accelerate the growth of MAD2 tumors, but it contributed to the tolerance of MAD2-induced detrimental effects on tumor cells." (PMID 37452072, 2023). "ETS1, though not in our list of significantly differentially expressed gene across all tumor types, regulates at multiple levels: at the level of E2F1, FOXM1 and PVT1, but due to its negative immunoreactivity in all tumor types, it may be doing so at gene/mRNA level." (PMID 30809433, 2019).
tumor (continued). "Overall, the current data show multiple targets of ZR30 for its tumor suppressive effect, including membrane receptors (EGFR, NOTCH1) and their downstream AKT-signaling, pro-invasive and pro-angiogenic extracellular protease (MMP2), and oncogenic transcription factor (FOXM1)." (PMID 29290950, 2017). "Moreover, overexpression of either OTUB1 or FOXM1 accelerated tumorigenesis and elevated tumor weight, which could be further enhanced by co-overexpression of OTUB1-FOXM1 but not OTUB1-FOXM1MutKEN (p<0.01)." (PMID 27167337, 2016). "Analyses of FOXM1 expression in tumor samples of diverse origins have consistently demonstrated a tight correlation between FOXM1 upregulation and enhanced tumorigenic potential but most studies have not addressed whether FOXM1b and FOXM1c are differentially regulated." (PMID 23386997, 2013).
infection (13 papers, 2011 to 2025). The state of being infected such as from the introduction of a foreign agent such as serum, vaccine, antigenic substance or organism. "Gastric Foxm1 was also elevated at 6 months post-infection with H. pylori PMSS1, as well as in a different mouse strain and sex, C57BL/6 females, infected with H. pylori SS1 at 7–9 months post-infection." (PMID 38014984, 2024). "In C57BL/6J mice infected with H. pylori SS1, FOXM1 was elevated at a single time point of 8 months post-infection." (PMID 38014984, 2024). "Taken together, increased expression and activities of E2F1 and FOXM1 accounted for 40% of the transcriptome induced by BKPyV-infection." (PMID 35194151, 2022). "Expression of the late cell cycle-associated transcription factor FOXM1 was also induced by BKPyV infection and GSEA supported FOXM1-activity during infection." (PMID 35194151, 2022). "Previous studies have found that AT2 cells positive for Forkhead box M1 (FoxM1) and Stem cell antigen 1 (Sca1) function as stem cells after infection with Pseudomonas aeruginosa (PA), and differentiate to AT1s to play a repair role under the stimulation of Wnt signaling." (PMID 37166489, 2023). "In cultured VSMCs, treatment with PGE1-OH or infection of Ad-EP4 also significantly upregulated the mRNA levels of genes related to cell proliferation including Ki67, Foxm1, Ccna2, Ccnb1, Ccnd1, Ccnd2, Ccne1, and CDK2." (PMID 36078128, 2022). "Gastric Foxm1 was not elevated in INS-GAS male mice at 8 weeks or 5 months post-infection with H. pylori SS1 but was elevated by 6 months post-infection." (PMID 38014984, 2024).
adenocarcinoma (10 papers, 2009 to 2024). A common cancer characterized by the presence of malignant glandular cells. "To test the clinical significance of FoxM1 activation, we analyzed a cohort of KRAS mutant adenocarcinoma samples collected from patients undergoing surgical resection." (PMID 34573384, 2021). "Of the canonical changes noted, promoter (PR) DM loci with reciprocal changes in expression in adenocarcinomas included HBEGF, AGER, PTPRM, DPT, CST1, MELK; DM GB loci with concordant changes in expression included FOXM1, FERMT1, SLC7A5, and FAP genes." (PMID 26683690, 2015).
lung (6 papers, 2014 to 2023). "Moreover, following inflammatory lung injury, FOXM1 can promote endothelial and vascular repair and improve lung vascular permeability and lung functions, hinting at the reparative role of FOXM1." (PMID 36964598, 2023).
cardiovascular disease (4 papers, 2012 to 2025). "The miR-320b/FOXM1 axis may serve as a potential therapeutic target for early intervention in OSA-related cardiovascular disease." (PMID 41004495, 2025). "Moreover, our findings also highlight FOXM1 as a potential molecular target to prevent and treat cardiovascular diseases." (PMID 33171439, 2020). "Foxm1 expression has been previously shown to progressively decrease in fibroblasts from adult humans and to be down-regulated in fibroblasts from patients with Progeria syndrome, a rare disorder in which individuals prematurely show signs of aging including cardiovascular disease." (PMID 23144938, 2012).
inflammation (3 papers, 2012 to 2024). Aberrant reaction of the microcirculation characterized by movement of fluid and leukocytes from the blood into extravascular tissues. "To further determine the effects of FoxM1 expression on resolution of lung inflammation, we assessed the expression of proinflammatory cytokines and adhesion molecules." (PMID 23185540, 2012). "It was speculated that decreased FOXM1 expression would lead to reduced inhibition of inflammatory response, massive secretion of inflammatory factors and mediators, which then promote acute lung inflammation and exacerbate lung damage." (PMID 39711843, 2024).
digestive system tumors (2 papers, 2023 to 2024). "It has been reported that 17 genes play a key role in digestive system tumors, of which three are in the FOX family (FOXD1, FOXM1, and FOXQ1)." (PMID 38839744, 2024).
central nervous system disorder (1 paper, 2025). A disease involving the central nervous system. "In the context of central nervous system disorders, FoxM1 has been shown to mediate neuronal differentiation and protect against neurodegeneration." (PMID 41154771, 2025).
CNS tumor (1 paper, 2019). "An immunohistochemistry staining confirmed increased levels of FOXM1 expression in MB tumors in comparison to cerebellar control (biopsy specimens of a 6-year-old and a 46-year-old patient without CNS tumor)." (PMID 31541075, 2019).
hematologic cancers (1 paper, 2019). "Forkhead Box M1 (FOXM1) is an oncogenic transcription factor implicated in the pathogenesis of solid and hematologic cancers." (PMID 31390744, 2019). "Few published studies have specifically addressed the functional importance of FOXM1 in hematologic cancers." (PMID 31390744, 2019).
hematologic malignancies (1 paper, 2019). "In comparison, the biological significance of FOXM1 in hematologic malignancies is less well understood." (PMID 31390744, 2019). "The expression and biological significance of FOXM1 in hematologic malignancies have not been extensively investigated." (PMID 31390744, 2019).
respiratory disease (1 paper, 2011). "A subset of genes co-expressed with AQP4 and associated to respiratory disease were assigned to potential anti-tumorigenic function like CAV1, EDNRB, or SELENBP1, whereas genes more related to pro-tumorigenic function like CDK2, FOXM1, PLK1 or RRM1 were found to be anti-correlated with AQP4." (PMID 21548930, 2011).
vascular disorder (1 paper, 2024). A general term used to describe any disease affecting blood vessels]. "FOXM1 is a promising candidate for therapeutic intervention in several human malignancies and has a role in developing and treating several immune-related and vascular disorders." (PMID 38464517, 2024).
FOXM1 also shares sentences with these, for which no sentence is quoted: insulinoma (26 papers); Hyperglycemia (13); Hyperinsulinemia (8); multiple myeloma (6); type 2 diabetes mellitus (5); injury (4); idiopathic pulmonary fibrosis (3); infiltrating ductal breast carcinomas (3); intrahepatic cholangiocarcinoma (3); papillary thyroid carcinoma (3); skin cancer (3); acute myocardial infarction (2); acute respiratory distress syndrome (2); Atypical Meningioma (2); bile duct cancer (2); chronic obstructive pulmonary disease (2); clear cell carcinoma (2); dyslipidemia (2); endometrial adenocarcinoma (2); eosinophilic esophagitis (2); hepatitis B (2); Hutchinson-Gilford progeria syndrome (2); Hypoglycemia (2); Impaired glucose tolerance (2); kidney diseases (2); malignant rhabdoid tumors (2); maturity onset diabetes of the young (2); metabolic disorders (2); pulmonary edema (2); systemic lupus erythematosus (2).
A further 76 diseases each share a sentence with FOXM1 in 2 papers or fewer.